ADAM23 (ADAM metallopeptidase domain 23)
Diseases named in the same sentence as ADAM23 in open-access papers (continued):
Sharing a sentence is not in itself a finding about the gene and the disease.
glioma (1 paper, 2023). A benign or malignant brain and spinal cord tumor that arises from glial cells (astrocytes, oligodendrocytes, ependymal cells). "GSC23 and U87 cells amongst the glioma cells had the highest expression levels of ADAM23, as confirmed using IF assays." (PMID 38024245, 2023).
glomerulosclerosis (1 paper, 2007). A hardening of the kidney glomerulus caused by scarring of the blood vessels. "For UAE, we observed strong association with ADAM23, a gene involved in the metalloproteinase family, which may be involved in the pathophysiology of glomerulosclerosis, and PCDH9, a gene that is a member of the cadherin superfamily." (PMID 17903292, 2007).
head and neck cancer (1 paper, 2024). A primary or metastatic malignant neoplasm affecting the head and neck. "In sum, this study showed a significant causal role of genetically dysregulated ADAM23 protein with head and neck cancer risk." (PMID 38985358, 2024). "The identification of ADAM23 as a causal risk factor for head and neck cancer has important implications for risk stratification, early detection, and precision prevention strategies." (PMID 38985358, 2024). "Although our study results support a causal relationship between ADAM23 and head and neck cancer, we cannot currently determine the exact direction of causality." (PMID 38985358, 2024). "First, prospective studies are needed to validate the association between pre-diagnostic ADAM23 levels and head and neck cancer risk and evaluate its potential as an early detection biomarker." (PMID 38985358, 2024). "Future studies are warranted to address the causal mechanisms underlying the role of ADAM23 in mediating head and neck cancers, and its role as a potential therapeutic target and biomarker." (PMID 38985358, 2024). "Meanwhile, other plasma protein indicators related to ADAM23 are also worthy of attention, and there is hope to construct a combination model of protein biomarkers to improve the sensitivity and specificity of head and neck cancer risk prediction." (PMID 38985358, 2024). "One possible explanation is that elevated ADAM23 protein levels lead to an increased risk of head and neck cancer." (PMID 38985358, 2024). "Subsequent studies can further validate the correlation between ADAM23 levels and the risk of head and neck cancer in large sample cohorts and evaluate its potential as an early screening and diagnostic biomarker." (PMID 38985358, 2024). "Causal effects estimates further indicated a significant causal association between ADAM23 and head and neck cancer." (PMID 38985358, 2024). "The specific mechanisms underlying the role of ADAM23 in mediating head and neck cancer risk, and its role as a potential therapeutic target and biomarker, need further investigation." (PMID 38985358, 2024). "Taken together, the present study applied two-sample MR and highlighted a significant causal role of genetically dysregulated ADAM23 with head and neck cancer risk." (PMID 38985358, 2024). "Together, these results highlighted the causal role of ADAM23 in head and neck cancer." (PMID 38985358, 2024). "Furthermore, this study suggests that elevated plasma ADAM23 levels may be a risk factor for the occurrence of head and neck cancer, providing an important direction for the development of plasma protein biomarkers for head and neck cancer." (PMID 38985358, 2024). "Additionally, given the genetic architecture of head and neck cancer, it will be important to investigate whether the causal role of ADAM23 varies across molecular subtypes or is modified by environmental exposures." (PMID 38985358, 2024). "IVW model results showed a significant causal association between A Disintegrin and metalloproteinase domain-containing protein 23 (ADAM23) and head and neck cancer." (PMID 38985358, 2024). "A significant causal association between A Disintegrin and metalloproteinase domain-containing protein 23 (ADAM23) and head and neck cancer was noted." (PMID 38985358, 2024). "However, the biological mechanisms linking ADAM23 to head and neck cancer pathogenesis warrant further investigation through molecular and cell biology experiments." (PMID 38985358, 2024). "Considering its role in αvβ3 integrin activation, ADAM23 may be a potential biomarker for anti-integrin therapies in head and neck cancer, which have been a recent focus area of research." (PMID 38985358, 2024). "Additionally, functional experiments are needed to validate the specific mechanisms of action of ADAM23 in the development of head and neck cancer." (PMID 38985358, 2024). "ADAM23 may also be a potential molecular biomarker for screening and evaluating the efficacy of head and neck cancer drugs." (PMID 38985358, 2024).
head and neck cancer (continued). "The occurrence and development of head and neck cancer may, in turn, influence the expression levels of ADAM23, or there may be a bidirectional relationship with mutual influence between ADAM23 and head and neck cancer." (PMID 38985358, 2024). "In addition, rs1921673 has been mapped to ADAM23 expression; however, there is currently no literature directly linking this SNP to the risk of head and neck cancer." (PMID 38985358, 2024). "Moreover, understanding the biological pathways through which ADAM23 influences head and neck cancer development may inform the development of targeted interventions to mitigate its harmful effects." (PMID 38985358, 2024). "In addition, dynamically monitoring changes in ADAM23 levels may help evaluate the efficacy and prognosis of head and neck cancer." (PMID 38985358, 2024). "However, we cannot rule out the alternative possibility that ADAM23 gene polymorphisms affect head and neck cancer risk by altering protein levels." (PMID 38985358, 2024).
herpes simplex encephalitis (1 paper, 2025). Herpes simplex virus encephalitis (HSE) is caused by the infection of the central nervous system by Herpes simplex virus (HSV) that could have a devastating clinical course and a potentially fatal outcome particularly with delay or lack of treatment. "In this study, we identified a novel autoantibody targeting ADAM23 in a patient with post-herpes simplex encephalitis autoimmune encephalitis (post-HSE AE)." (PMID 40519920, 2025).
ischemic stroke (1 paper, 2022). A stroke disorder caused by obstruction of blood flow to the brain, due to thrombotic (local blood clot formation) or embolic (due to a blood clot or other material traveling from another site) event. "However, in a recent genome wide association study of neurological instability within the first 24 h after ischemic stroke (n = 5,876) a 2q33.3 loci including both ADAM23 and NRP2 reached genome-wide significance, with indication of ADAM23 driving the association." (PMID 36418382, 2022).
metastatic disease (1 paper, 2018). "After experimental validation of the association between the lower values of SNAI2 and ADAM23 methylation and clinical features of aggressive BCs, these methylation profiles could improve the management of metastatic disease." (PMID 30189837, 2018).
neuropathy (1 paper, 2021). A disorder affecting the nervous system that manifests with pain, tingling, numbness, and/or muscle weakness. "However, the deregulation of ADAM23 has a good chance to be implicated in clinical neuropathy presentations in WM as well as in IgM MGUS." (PMID 33921415, 2021).
oesophageal cancer (1 paper, 2021). "We hypothesized that, in the microenvironment of oesophageal cancer tissues, a depressive state would upregulate ADAM23 by downregulating LGI1 expression." (PMID 35003396, 2021).
osteoporosis (1 paper, 2023). A condition of reduced bone mass, with decreased cortical thickness and a decrease in the number and size of the trabeculae of cancellous bone (but normal chemical composition), resulting in increased fracture incidence. "Second, our negative results could not totally deny the potential of ADAM12, ADAM19, ADAM23 and ADAMTS6 as biomarkers for osteoporosis due to the weakness of MR analysis in identifying non-linear relationship." (PMID 37468870, 2023).
Parkinson disease (1 paper, 2023). A progressive degenerative disorder of the central nervous system characterized by loss of dopamine producing neurons in the substantia nigra and the presence of Lewy bodies in the substantia nigra and locus coeruleus. "We combined WGCNA and random forest algorithm to obtain two new FRHGs (NUPR1 and ADAM23) in Parkinson’s disease, which are expected to be new PD biomarkers and drug action targets." (PMID 38127902, 2023). "We obtained eight Parkinson’s disease ferroptosis-related genes (MAP3K11, SNX4, SIRT2, NUPR1, ACSL4, CISD1, ADAM23 and NEDD4L) by taking intersections of key genes of these two PD modules with ferroptosis-related genes." (PMID 38127902, 2023). "We first tested the accuracy of two machine learning-built models and finally chose to use the random forest to obtain five Parkinson’s disease FRHGs (CISD1, SIRT2, NUPR1, ADAM23 and NEDD4L)." (PMID 38127902, 2023). "The top 5 genes were extracted as FRHGs in Parkinson’s disease (CISD1, SIRT2, NUPR1, ADAM23 and NEDD4L)." (PMID 38127902, 2023). "The Yellow module yielded three FRGs in Parkinson’s disease (CISD1, ADAM23 and NEDD4L)." (PMID 38127902, 2023).
psoriasis vulgaris (1 paper, 2016). Plaque psoriasis is the most common presentation of psoriasis. "Surprisingly we found a higher expression of several genes involved in neural pathways (e.g. GPRIN and ADAM23) in PPP/PPPP as compared to psoriasis vulgaris and normal acral skin." (PMID 27152848, 2016).
tumor (20 papers, 2008 to 2026). "In the present study, we investigated promoter methylation in six genes associated with tumour invasivity (ADAM23, uPA, CXCL12, TWIST1, SNAI1 and SNAI2)." (PMID 30189837, 2018). "Transcriptomic profiling identifies ADAM23, a cell-adhesion-related tumor suppressor, as a METTL3-dependent, m6A-associated transcript, with altered mRNA expression observed across multiple experimental systems and several high-confidence predicted m6A sites within its transcript." (PMID 41677656, 2026). "In addition, ADAM23 knockdown was associated with an enhanced pulmonary tumor cell arrest in immunodeficient mice." (PMID 30647853, 2018). "ADAM23 silencing plays a key role in tumor metastasis and progression by downregulating αvβ3 integrin activation." (PMID 38985358, 2024). "In like manner, HPβCD binding to ADAM23 potentially facilitates tumour suppression due to its adhesive function." (PMID 37345165, 2023). "Equally important, ADAM23 knockdown decreases proliferation and delays tumor growth, while increasing survival in mouse hosts and LGA." (PMID 38024245, 2023). "Accordingly, GO annotations of gene sets inversely correlated with ADAM23 mainly included terms related to tumor invasiveness and AD." (PMID 38024245, 2023). "Among them, ADAM23 is considered to be a possible tumor suppressor gene and is often downregulated in various malignant tumors." (PMID 34163353, 2021). "It is also noteworthy that ADAM22 is highly homologous to ADAM23, and the two are thought to have similar tumour suppressor functions." (PMID 35003396, 2021). "For example, ADAM23 is considered a tumor suppressor and it is epigenetically inactivated by promoter methylation in BC patients." (PMID 31683635, 2019). "No miRNA regulating its encoding gene has yet been identified; however, we previously published that ADAM23 most likely participates in the spread of mesenchymal circulating tumor cells." (PMID 31683635, 2019). "ADAM23 can also bind to αvβ3 integrin and negatively modulate the function of αvβ3 activation, resulting in tumor metastasis." (PMID 28828010, 2017). "Further studies, aimed to produce antibodies to ADAM23, are necessary to prove its suitability as a tumor vascular target." (PMID 18447899, 2008). "Accordingly, we suggest that lower levels of ADAM23 may facilitate the emergence of a brain infiltrative tumor phenotype in preclinical models and human patients." (PMID 38024245, 2023). "Thus, ADAM23 interacts with different ligands and receptors in a cell type-specific manner and triggers different signaling pathways, resulting in, e.g., tumor metastasis, cell proliferation and differentiation, but also in the suppression of neuronal fate." (PMID 28828010, 2017). "Our evidence of a high expression of ADAM23 by TdEC suggests that this protein might be important for establishing contacts and promoting adhesive functions during the pathological processes leading to the formation of new blood vessels within the tumor." (PMID 18447899, 2008). "ADAM23, the member of a disintegrin and metalloproteinase (ADAM) family, is a significant focus of attention, owing to its expression in many tumor types." (PMID 40369674, 2025). "A disintegrin and metalloprotease 23 (ADAM23), a member of the ADAM family, is considered a possible tumour suppressor gene, and is frequently down‐regulated in various types of malignancies." (PMID 33949771, 2021). "The results showed that 5 proteins (ADAM23, ARHGAP20, ICOS, IRF4,MMRN1) were significantly different in tumour tissues compared with normal tissues." (PMID 33949771, 2021). "In order to investigate the in vivo localization of ADAM23, GPNMB and PRSS3, human tumor tissues were analyzed by in situ hybridization." (PMID 18447899, 2008). "Under both conditions the expression of ADAM23, FAP, GPNMB and PRSS3 genes was much higher in EC isolated from tumor specimens, as shown by the fold difference values." (PMID 18447899, 2008).
tumor (continued). "ADAM23 and ARHGEF26-AS1 are tumour suppressor genes, and miR-372-3p may have a procarcinogenic effects." (PMID 35003396, 2021). "Finally, 19 prognostic genes were verified by GSE17536 and GSE17537 from GEO, and five genes (ADAM23, ARHGAP20, ICOS, IRF4,MMRN1) were significantly different in tumour tissues compared with normal tissues at the protein level." (PMID 33949771, 2021). "We found significantly lower ADAM23 methylation levels in tumours of CTC-positive patients, regardless of their epithelial or mesenchymal phenotype, than in tumours of patients with LNM." (PMID 30189837, 2018). "Finally, many of the genes down-regulated by EZH2 GOF in this study that modulate ECM-adhesion/signaling display altered expression or have been ascribed roles in tumor biology (e.g. NRCAM, CEACAM1, SORCS1, ADAM23, MME)." (PMID 25671303, 2015). "They demonstrated marked micro-regional heterogeneity within a single tumor mass with respect to a particular proteinase, ADAM-23, showing further that ADAM-23 positive and ADAM-23 negative subpopulations had different but mutually supporting functions." (PMID 25211298, 2014). "Here we describe for the first time a much higher expression of ADAM23, FAP, GNPNB and PRSS3 in EC derived from six tumor samples than in EC from four normal tissue specimens examined by real-time PCR, whose origin differed from that investigated by microarray analysis." (PMID 18447899, 2008). "In the context of our results, we consider that decreased methylation of the ADAM23 gene could partially represent the molecular profile of EC from the tissue surrounding the tumour body rather than from the tumour cells." (PMID 30189837, 2018). "A significant correlation exists between tumor stage, lymph node metastasis, and reduced PFS and OS in OC patients lacking ADAM23 expression." (PMID 40369674, 2025). "Therefore, patients with higher ADAM23 expression levels, which may be the result of decreased promoter methylation, could have contributed to the dense development of tumour blood vessels, resulting in the haematogenous rather than the lymphogenous spread of cancer cells." (PMID 30189837, 2018). "Of these mRNAs, the ADAM23, FAP, GPMNB and PRSS3 were found in the tumour-derived endothelium, but no expression was observed in tumour cells." (PMID 30189837, 2018). "ADAM23 and GPNMB were expressed by a limited subset of tissues, while tumor cells did not express either one of them." (PMID 18447899, 2008).
cancer (18 papers, 2008 to 2024). A tumor composed of atypical neoplastic, often pleomorphic cells that invade other tissues. "The hypermethylation of ADAM-23 has been associated with more advanced cancer of the larynx." (PMID 38985358, 2024). "Moreover, promoter hypermethylation of the ADAM23 gene in breast PTs is significantly associated with more advanced grade, higher proliferation of cancer cells, poor prognosis and lower survival rates." (PMID 30189837, 2018). "On the other hand, variances in ADAM23 methylation profiles among BC patients with different routes of cancer cell dissemination suggest that ADAM23 plays a role in hematogenous spread, which involves the migration of cancer cells through the bloodstream." (PMID 38317965, 2024). "Promoter hypermethylation of ADAM23 was observed in cancers that was strongly correlated with declines in expression levels of both of the mRNA and protein." (PMID 38317965, 2024). "On the other hand, Adam23 has been demonstrated to suppress cancer cell metastasis through the interaction with integrins." (PMID 34193044, 2021). "In our previous study of methylation profiles in 206 BC patients we showed that the risk for LNMs development and higher proliferation of cancer cells was increased by hypermethylation of CXCL12 and ADAM23 genes, respectively." (PMID 30189837, 2018). "The relationships between the decreased methylation levels of the SNAI2 and ADAM23 genes and cancer de-differentiation and haematogenous dissemination, respectively, indicate novel functions of those genes in the invasive processes." (PMID 30189837, 2018). "Among the ADAM proteins, proteolytically inactive ADAM23 negatively regulates cancer cell migration by binding αvβ3 integrin to its disintegrin domain." (PMID 30189837, 2018). "Particularly, ADAM23 suppresses cancer cell progression through interaction with αvβ3 integrin; the upregulation of ADAM23 in this study due to ADK-L knockdown may facilitate this effect." (PMID 31921385, 2019). "The differences in ADAM23 methylation profiles in BC patients with various route of cancer cells dissemination suggest that ADAM23 could participate in haematogenous spread." (PMID 30189837, 2018). "Secondly, metalloprotease and adhesion molecules, MMP9 and ADAM23, are involved in the breakdown of the extracellular matrix in physiological processes such as embryonic development, reproduction, and tissue remodeling; they also play an important role in metastasis of cancer." (PMID 31921385, 2019). "In vivo investigation by in situ hybridization established that ADAM23, GPNMB and PRSS3 expression is localized on blood vessels of human cancer specimens." (PMID 18447899, 2008). "Moreover, ADAM23, GPMNB and PRSS3 expression only occurred in the blood vessels of human cancer samples." (PMID 30189837, 2018). "Cancer cells not expressing ADAM23 have higher migration capacities in cell line models." (PMID 30189837, 2018). "Our results also revealed that ADAM23 was not expressed in cancer cells." (PMID 18447899, 2008).
CNS tumors (1 paper, 2023). "Downregulation of ADAM23 expression in CNS tumors was validated in the public Rembrandt database." (PMID 38024245, 2023).
myopathy (1 paper, 2025). A disease of the muscle in which the muscle fibers do not function properly. "Furthermore, we report the first ADAM23 variant associated with lethal neonatal-onset epilepsy and myopathy." (PMID 40455867, 2025).
neurological disorders (1 paper, 2023). "ADAM23, ANKRD11, and MACROD2 function in the nervous system and are associated with several neurological disorders." (PMID 37805653, 2023).